AGR2 (anterior gradient 2, protein disulphide isomerase family member)
Diseases named in the same sentence as AGR2 in open-access papers (continued):
Sharing a sentence is not in itself a finding about the gene and the disease.
pancreatic cancer (continued). "We used ELISA to measure AGR2 levels in pancreatic juice samples from patients with benign pancreatic diseases (n = 18; including chronic pancreatitis), premalignant pancreatic neoplasia (n = 25; including PanIN2, PanIN3, and IPMNs), and pancreatic cancer (n = 8)." (PMID 20550709, 2010). "To evaluate the therapeutic synergy between ferroptosis induction and AGR2 ablation, we conducted assessments of IKE—a metabolically stabilized derivative of the ferroptosis inducer erastin—in orthotopic pancreatic cancer models." (PMID 41326375, 2025). "For example, the secreted protein AGR2 is primarily engaged in cell invasion, motility, drug sensitivity, metastasis, and growth of PANC-1 pancreatic cancer cells and the invasion of colorectal cancer cells." (PMID 39682235, 2024). "According to the cBioPortal software information, several correlations between AGR2 and ER stress-related factors have been demonstrated in numerous cancer types, such as HCC and lung, breast and pancreatic cancers." (PMID 36899352, 2023). "In conclusion, the results of the present study indicate that extracellular AGR2 markedly promotes cell migration, invasion, and proliferation in PANC-1 pancreatic cancer cells." (PMID 33413231, 2021). "Together with our findings that secreted AGR2 promotes PANC-1 cell migration, invasion, and proliferation, these data suggest that extracellular AGR2 plays a key role in pancreatic cancer initiation and progression." (PMID 33413231, 2021). "The aim of the following study is to explore the contribution and possible mechanism of intracellular and extracellular AGR2 to cell proliferation, migration, invasion, and survival in PANC-1 pancreatic cancer cells." (PMID 33413231, 2021). "Secreted AGR2 is predominantly involved in cell proliferation, migration and invasion in PANC-1 pancreatic cancer cells." (PMID 33413231, 2021). "Based on the biochemical structure of AGR2 protein, PANC-1 pancreatic cancer cells stably expressing ER-resident or secreted AGR2 were generated by a lentivirus-mediated stable overexpression system." (PMID 33413231, 2021). "A series of experiments was performed to examine the relationship between AGR2 and the ERK/AKT pathways in pancreatic cancer cells (PCa)." (PMID 31247903, 2019). "Additionally, elevated AGR2 protein expression is observed in numerous cancer types including gastric adenocarcinoma, breast, non-small cell lung, ovarian, esophageal, prostate, and pancreatic cancer, and overexpression of the AGR2 protein is correlated with poor prognosis in these carcinomas." (PMID 30406031, 2018). "Enhanced AGR2 expression and EGFR signaling are also universally present in human pancreatic cancer, which support a linkage between tissue injury, regeneration, and cancer pathogenesis." (PMID 27764193, 2016). "We propose that AGR2-induced EGFR signaling is a common and essential link between injury-induced tissue regeneration and the development of pancreatic cancer." (PMID 27764193, 2016). "Elevated levels of AGR2 resulting from ERS have been discovered in pancreatic fluid from patients with ductal complex and early-stage high-grade pancreatic intraepithelial tumors, indicating a precursor to aggressive pancreatic cancer." (PMID 39062458, 2024). "Taken together, these results demonstrate that secreted AGR2, but not intracellular AGR2, is associated with cell migration, invasion, and proliferation of PANC-1 pancreatic cancer cells under physiological conditions." (PMID 33413231, 2021). "In primary cells derived from human patient-derived xenograft (PDX) model, flow-cytometry revealed that AGR2 was overexpressed in pancreatic cancer stem cells (CSC) compared with non-stem cancer cells." (PMID 27941872, 2017).
pancreatic cancer (continued). "In addition, upregulation of AGR2 promotes the expression of MUC1, which acts as an important regulator of the metabolism of pancreatic cancer cells." (PMID 27322206, 2016). "Likewise, inhibition of AGR2 and EGFR expression with RNA interference in pancreatic cancer cell lines reduced cell viability and the transformed phenotype." (PMID 27764193, 2016). "RT-qPCR analyses showed that AGR2 mRNA levels were over 2-fold and 20-fold higher in pancreatic tumor tissues than unpaired and paired non-tumor tissues." (PMID 27322206, 2016). "In the current study, four pancreatic cancer biomarker candidates (SYCN, REG1B, AGR2 and LOXL2) delineated through our previous integrated proteomics analysis of cell line conditioned media and pancreatic juice, were validated in two sample sets of serum/plasma containing a total of 432 samples." (PMID 24007603, 2013). "AGR2 was highly expressed in the PanIN ducts from both PanIN cases a and c, and also highly expressed (strong staining) in pancreatic cancer, but not in normal pancreas epithelium (negative staining)." (PMID 20550709, 2010). "While AGR2 levels were significantly elevated in the pancreatic juice from premalignant and pancreatic cancer patients, serum levels of AGR2 did not distinguish patients with premalignant or pancreatic cancer from control patients." (PMID 20550709, 2010). "Moreover, EGFR expression and activation are not involved in AGR2 pro-oncogenic roles in PANC-1 pancreatic cancer cells." (PMID 33413231, 2021). "Furthermore, consistent with the results obtained from miR-1291-expressing pancreatic cancer cells (this study), both FOXA2 and AGR2 protein levels were reduced in cells after transient transfection with miR-1291 expression plasmids (data not shown) or bioengineered miR-1291 agent." (PMID 27322206, 2016). "However, to the best of our knowledge, evaluation of AGR2 protein in plasma or other biological fluids has not been reported in pancreatic cancer." (PMID 20550709, 2010). "And this could explain why pancreatic cancer patients do not have higher juice AGR2 level than the PanIN patients, while they have strong AGR2 staining in the cancer tissues." (PMID 20550709, 2010). "Therefore, AGR2 levels were not significantly different between pancreatic cancer sera and sera from cancer-free controls (p = 0.27)." (PMID 20550709, 2010). "Notably, although ectopic expression of AGR2 almost fully rescued its expression in H-1-2-treated pancreatic cancer cells to comparable level as untreated cells, it did not completely abolish the beneficial effect of H-1-2 on pancreatic cancer cells." (PMID 32322663, 2020). "MRNA levels of AGR2, TFF1, and FXYD3 were greatly increased in pancreatic cancer cells when compared with non-cancerous cells." (PMID 39682235, 2024). "Using this approach and verifying the data using individual gene expression data, we found that AGR2, CEACAM6, GNMT, PDIA2, POSTN, RBPJL, and S100P are upregulated in pancreatic tumor tissue as compared to non-tumor tissue from Black and White patients." (PMID 36812168, 2023).
lung carcinoma (34 papers, 2014 to 2026). "Previous studies have noted that AGR2 is expressed in many solid tumor types, including prostate, pancreatic, breast and lung cancer, and that the overexpression of AGR2 is closely associated with the growth, metastasis and survival of tumors (PMID: 27283903)." (PMID 34793477, 2021). "AGR2 protein is highly expressed in various human cancers including lung cancer, which is associated with poor patient survival and also confirmed in our analysis." (PMID 30647455, 2019). "Another interesting candidate is AGR2, which has been associated with lung cancer, as a prognostic marker." (PMID 31429720, 2019). "The method of semi-quantitative assessment of AGR2 activity in human lung cancer on our OPA samples showed similar values." (PMID 40941427, 2025). "AGR2 is highly expressed in a variety of adenocarcinomas, including prostate, breast, and lung cancers and others." (PMID 39727484, 2024). "A recent report revealed that proteasome inhibitor MG132/bortezomib suppressed AGR2 expression in an ER stress-independent manner and proteasome inhibitor-induced AGR2 degradation via activation of autophagy in lung cancer." (PMID 35055132, 2022). "Several studies have identified AGR2 as a potential oncology biomarker and a potential drug target in lung cancer, cervical carcinoma, and chronic myelogenous leukemia." (PMID 35055132, 2022). "In lung cancer cells, AGR2 knock-down led to the re-organization of F-actin and increased the formation of stress fibers." (PMID 33717413, 2021). "In contrast, our data clearly demonstrate that AGR2 expression is suppressed by ZEB1 expression in lung cancer cells." (PMID 32570918, 2020). "The overexpression of ZEB1 decreased the promoter activity of the AGR2 gene, which resulted in reduced AGR2 protein level and the acquisition of a more invasive phenotype of these lung cancer cells." (PMID 32570918, 2020). "We show that lung cancer cells A549 with endogenous expression of AGR2, when injected subcutaneously, form more easily primary tumors compared to A549 cells with AGR2 gene knockout which generate significantly smaller tumors." (PMID 32570918, 2020). "In lung cancer cells, AGR2 was shown to play a role in the preneoplastic phenotype, thus contributing to epithelial tumorigenicity and promoting the acquisition of invasive and metastatic features." (PMID 31247903, 2019). "Driven by these observations, we next verified if there is a correlation between the AGR2 protein and autophagy in lung cancer cell lines." (PMID 30647455, 2019). "Although high AGR2 expression in breast and lung cancer was reportedly correlated with poor clinical prognosis, some studies suggested the otherwise, thus resulting in a controversy." (PMID 29138453, 2017). "For example, healthy lung cells and lung cancer cells were grown into miniature replicas of lung organs in the laboratory, and in a key experiment, AGR2 was added to the lung organoids grown from the healthy cells." (PMID 27240165, 2016). "One of these protein folders is called anterior gradient-2 (or AGR2 for short) and is produced at high levels in so-called epithelial cancers, such as breast and lung cancer." (PMID 27240165, 2016). "To evaluate the correlation between AGR2 expression levels and lung cancer, we monitored AGR2 endogenous expression in a panel of human lung bronchial epithelial cell lines." (PMID 27240165, 2016).
lung carcinoma (continued). "Taken together, these results demonstrate in vitro and in vivo correlations between AGR2 expression levels and lung cancer, suggesting a function for this protein in tumor development, progression and aggressiveness." (PMID 27240165, 2016). "Presence of AGR2 protein in serum and AGR2 expression in circulating tumor cells have been reported in patients of ovarian and lung cancer." (PMID 25367337, 2014). "To support the involvement of AGR2 in arachidonic acid metabolism, we screened publicly accessible colorectal and lung cancer gene expression datasets (Cancer Cell Line Encyclopedia and COSMIC) and correlated AGR2 mRNA levels with expression of genes directly involved in prostaglandin biosynthesis." (PMID 36142758, 2022). "Interestingly, we observed that addition of exogenous PGE2 elevated AGR2 protein in A549 lung carcinoma cells, with a similar trend observed in the colorectal cancer cell line HT-29." (PMID 36142758, 2022). "Therefore, we selected lung cancer cell lines A549 and H1299 differing in AGR2 expression to study in more detail the crosstalk between ZEB1 and AGR2 proteins." (PMID 32570918, 2020). "However, in the late and metastatic stages of lung cancer, expression profiles are changed in favor of ZEB1, which is associated with a decreased level of AGR2." (PMID 32570918, 2020). "Also, both intracellular overexpression of AGR2 and recombinant AGR2 supplementation to the cell culture medium promoted the cell growth of lung cancer." (PMID 33005802, 2020). "This notion may provide an additional explanation why AGR2 expression is relative high in human lung cancers where impaired autophagy was observed." (PMID 30647455, 2019). "FOXM1 directly activated the AGR2 gene, a key regulator of mucinous phenotype in lung cancer cells." (PMID 29267283, 2017). "Although the oncogenic functions of AGR2 remain largely unknown, AGR2 expression was demonstrated to be prognostic in human lung cancer." (PMID 29267283, 2017). "Although not as strong a finding, patients with stage I cancer also showed poorer survival with higher levels of AGR2, which could suggest a deleterious role for AGR2 in lung cancer." (PMID 26445321, 2015). "Lung cancer expression of AGR2 has prognostic value for younger patients." (PMID 26445321, 2015). "AGR2 could potentially become a viable serum biomarker for lung cancer." (PMID 26445321, 2015). "In lung cancer cells, MG132 led to autophagic degradation of the anterior gradient protein 2 homologue (AGR2)." (PMID 39080182, 2024). "In conclusion, our datasets provide a comprehensive insight into the transcriptome of A549 lung cancer cells after manipulation of AGR2 expression and/or TGF-β treatment, which extends our previous findings describing the role of AGR2 in the lung cancer model." (PMID 36142758, 2022). "Here, we observed that AGR2 expression is significantly suppressed by proteasome inhibitor MG132/bortezomib at mRNA and protein levels in lung cancer cells." (PMID 30647455, 2019). "There were significantly more AGR2-positive colorectal and non-small cell lung cancer BMs than expected (P<0.001), but fewer OPN-positive lung cancer BMs of all types (P=0.033)." (PMID 27100728, 2016). "A transcriptomic approach in lung cancer cells (A549) knocked‐out for AGR2 or not and treated or not with TGF‐β treatment unveiled significant changes in transcripts related to focal adhesions and arachidonic acid metabolism, two pathways involved in EMT." (PMID 37409695, 2023). "Here, we performed transcriptomic profiling of A549 lung cancer cells with CRISPR-Cas9 mediated AGR2 knockout with and without TGF-β treatment." (PMID 36142758, 2022). "Unlike urothelial carcinoma cells, where AGR2 expression is frequently absent, the lung cancer cells retain AGR2." (PMID 26445321, 2015).
lung carcinoma (continued). "Therefore, to further determine how AGR2 influences signaling pathways in cancer, A549 derived lung cancer cell line clones with or without AGR2 expression and with or without TGF-β treatment were subjected to RNA sequencing (RNAseq)." (PMID 36142758, 2022). "In lung cancer, AGR2 can modulate EGFR-TKI resistance in EGFR-mutant non-small cell carcinoma." (PMID 36327302, 2022). "Similarly, AGR2 expression was also found in non-hormone dependent cancers such as oesophageal cancer, gastric cancer, lung cancer and head and neck cancer." (PMID 33005802, 2020). "Bladder tumor AGR2 expression in the TMA cohort was not correlated with patient survival, unlike what has been found in prostate and lung cancer." (PMID 26894971, 2016).
ovarian carcinoma (26 papers, 2010 to 2026). A malignant neoplasm originating from the surface ovarian epithelium. "Moreover, aberrant methylation of hub gene AGR2 was reported to be associated with ovarian cancer, while MT3 was a putative tumor suppressor gene in pediatric acute myeloid leukemia." (PMID 32064261, 2020). "One recent study showed that increased AGR2 in plasma is associated with ovarian cancer." (PMID 20550709, 2010). "In this study, electrochemical-based panel immunosensors were prepared for the simultaneous determination of four potential biomarkers of ovarian cancer (AGR2, GLY, FOLR1, and SMRP)." (PMID 41518408, 2026). "For the first time in this study, an electrochemical panel immunosensor system was prepared using HSPEs for the simultaneous determination of potential ovarian cancer biomarkers AGR2, GLY, FOLR1, and SMRP." (PMID 41518408, 2026). "It has been shown to reduce AGR2 expression in ovarian cancer, thereby suppressing cell proliferation, migration, and invasion when used alone, and inhibiting tumor growth and metastasis in vitro and in vivo when combined with paclitaxel." (PMID 41011271, 2025). "Meanwhile, the protein level of AGR2 in the blood of ovarian cancer patients, including early-stage ovarian cancer patients, are significantly elevated compared to those in the blood of the general population." (PMID 39281319, 2024). "A murine model was established to investigate the metastasis of human ovarian cancer, thus demonstrating an increase in mRNA expression and a decrease in methylation at the CpG site within the AGR2 gene promoter region in metastatic tumor tissue." (PMID 39281319, 2024). "ETR was shown to have anti-cancer effects in an ovarian cancer model, possibly by impacting autophagic degradation of Anterior gradient protein 2 homolog (AGR2)." (PMID 39082334, 2024). "Immunohistochemical staining of AGR2 was also performed on different ovarian tissues, showing that AGR2 was expressed in 78.6% of ovarian carcinomas, 100% of BOTs and 0% of normal ovarian epithelium." (PMID 39281319, 2024). "AGR2 is overexpressed in numerous cancers, including breast, gastric, prostate, lung, and ovarian cancers." (PMID 35055132, 2022). "In summary, etravirine effectively suppresses ovarian cancer progression by promoting AGR2 autophagy degradation." (PMID 35055132, 2022). "A humanised monoclonal antibody has been developed to target extracellular AGR2 (eAGR2) and tested in mouse xenografts of the SK-OV-3 human ovarian carcinoma cell line (derived from ascitic fluid)." (PMID 34452625, 2021). "SK-OV-3 human ovarian carcinoma cells (derived from the ascitic fluid) display very low AGR2 expression level when cultured in vitro but produce large amounts of AGR2 during the generation of xenograft tumours in vivo." (PMID 34452625, 2021). "It has also been shown that AGR2 is secreted from tumour ovarian cells (SK-OV-3 ovarian cancer cell line derived from ascites fluid) and accumulates in the tumour interstitial fluid in EOC xenograft tumours." (PMID 34452625, 2021). "The overexpression of AGR2 in the human ovarian cancer cell line MDAH-2774 enhanced cell proliferation and invasion." (PMID 31247903, 2019). "In ovarian-related cancers, the plasma concentration in 46 samples of patients with ovarian cancer and 61 controls were tested for the immunoreactivity of AGR2, and the results revealed significantly high levels of AGR2 in the cancer cases." (PMID 31247903, 2019).